BDNF (brain derived neurotrophic factor)
Diseases named in the same sentence as BDNF in open-access papers (continued):
Sharing a sentence is not in itself a finding about the gene and the disease.
depression (continued). "Some previous studies reported that plasma BDNF was significantly increased in the responders to drugs with major depressive disorders, and some found that BDNF Val66Met Met allele has been associated with depression." (PMID 37485797, 2023). "BDNF and serotonin are both associated with the ability to promote the growth and maturation of neurons involved in mood disorders such as depression and anxiety." (PMID 38264193, 2023). "Studies using animals to model depression indicate that BDNF plays a crucial role in the underlying mechanisms of this illness." (PMID 37631295, 2023). "BDNF has been implicated in psychiatric disorders, including depression, because of its important role in brain development and neuroplasticity." (PMID 37631092, 2023). "Our results revealed decreased plasma BDNF concentrations in patients with various forms of depression compared to healthy controls, and increased plasma BDNF levels associated with response and remission to BLT in TRD patients." (PMID 37759825, 2023). "The level of BDNF has been shown to correlate with the expressions of depression‐associated miRNAs, such as miR‐30a." (PMID 37101380, 2023). "In conclusion, numerous studies have established significant connections between specific variations of BDNF/BDNF-AS gene polymorphisms and psychiatric disorders such as bipolar disorder, schizophrenia, and major depressive disorder." (PMID 37763162, 2023). "Our findings revealed that LPS induces stress, which causes depression-like behavior along with decreased expression of BDNF in the LPS group." (PMID 36909194, 2023). "A reduction in BDNF is commonly implicated in regional atrophy where depression has been associated with reduced hippocampal volume, impaired hippocampal neurogenesis, and hypoactivity of the dorsolateral prefrontal cortex." (PMID 37457896, 2023). "Disruption of synaptic plasticity is one of the pathogenic mechanisms of depression, and BDNF, as a synaptic modulator, has an important role in the treatment of depression." (PMID 38067664, 2023). "The BDNF–TrkB signaling is associated with normal brain function and some diseases such as Alzheimer’s disease, depression, and pain." (PMID 36818656, 2023). "The downregulation of BDNF can lead to increased oxidative stress, neuroinflammation, and neuro-apoptosis, which can cause long-lasting mental disorders such as anxiety, depression, and cognitive impairment." (PMID 37408184, 2023). "Research on BDNF has mostly focused on neurodegenerative diseases or depression, while only a few researchers have linked it to lung disease." (PMID 37909847, 2023). "A decrease in BDNF expression has been linked to several psychiatric disorders including schizophrenia and depression." (PMID 36766691, 2023). "For example, changes in exon IV methylation levels are implicated in depression, while some antidepressants can promote BDNF transcription." (PMID 37238659, 2023). "BDNF has been implicated in the development of depression, and its expression is influenced by the activity of many antidepressants." (PMID 36819781, 2023). "They discovered a notable correlation between the BDNF gene variant rs6265 and the intensity of depression." (PMID 37763162, 2023). "The study also found that BDNF gene polymorphism is associated with the antidepressant efficacy of ketamine in patients with depression." (PMID 36769799, 2023). "Further, animal models have revealed that depression-like behavior is associated with reduced BDNF expression in certain murine brain areas." (PMID 37719598, 2023). "Studies on early-onset depression consistently point to the importance of 5-HTTLPR and BDNF Val66Met polymorphisms in the susceptibility to early-onset depression." (PMID 34590201, 2023). "Exercise also upregulates growth factors, such as brain-derived neurotrophic factor, which is associated with depression and suicidal ideation." (PMID 37743985, 2023).
depression (continued). "On the other hand, several studies have associated BDNF/TrkB signaling with depression and antidepressant drug action." (PMID 36818650, 2023). "Recent evidence suggests that BDNF is associated with cognitive dysfunction and is decreased in various neurologic and psychiatric disorders like depression, Alzheimer’s disease, and Parkinson’s disease." (PMID 36787304, 2023). "A large meta-analytical study based on the studies performed on adults has proven that Val66Met polymorphism of the BDNF gene increases the risk of depression through influencing sensitivity to exposure to stressful life events." (PMID 34590201, 2023). "BDNF and its specific receptor TrkB are essentially linked with depression pathophysiology and mechanisms of antidepressants." (PMID 37799103, 2023). "Depression severity was associated positively with BDNF mRNA and negatively with BDNF protein in the remission group." (PMID 36984890, 2023). "The results of many clinical and animal studies confirm that disturbed neurotrophic factor systems, especially BDNF, and inflammation are two important risk factors in the pathogenesis of depression." (PMID 38069144, 2023). "In this study, the authors found that lower plasma BDNF concentrations were associated with higher scores on specific dimensions of mood disorders, notably Depression-Dejection (as measured by the Profile of Mood States, POMS)." (PMID 37693812, 2023). "Recently, brain-derived neurotrophic factor (BDNF) gene polymorphisms have been reported to play important roles in depression and cognitive impairment." (PMID 37415688, 2023). "BDNF is the most abundant neurotrophic factor in the body, and its association with depression has also recently been confirmed." (PMID 37598200, 2023). "Second, serum BDNF levels are influenced by platelets, and some studies have demonstrated an association amongst depression, CVD, and platelet function." (PMID 37895349, 2023). "The brain-derived neurotrophic factor (BDNF) val66met polymorphism is associated with an antidepressant response in patients with depression." (PMID 37784199, 2023). "Response to duloxetine was associated with a higher baseline serum BDNF level and greater reduction of the Hamilton Rating Scale for Depression (HAMD) scores for MD." (PMID 36831119, 2023). "BDNF is one of the neurotrophic factors reported to be associated with depression, Alzheimer’s disease, and cognitive functions (such as memory and learning) and is also reported to be decreased in individuals with dementia." (PMID 37242280, 2023). "A clinical study proved that individuals with BDNF val66met genotype exhibit decreased secretion of BDNF, accompanied by deficits in episodic memory function and increased risk of anxiety and depression." (PMID 37266540, 2023). "Decreased BDNF has been linked with depression in rigorous meta-analyses, though the effect size of this association is relatively small." (PMID 37693812, 2023). "It is known that BDNF in some other regions than the hippocampus (medial prefrontal cortex, nucleus accumbens, etc.)is also implicated in the pathophysiology of depression." (PMID 37603290, 2023). "The mechanism of action of sake yeast in decreasing depression-like and anxiety-like behaviors can be associated with sake’s effects on BDNF and antioxidant factors, as will be discussed." (PMID 39484298, 2023). "Neurotrophic factor BDNF has also turned out to be significantly associated with depression in clinical patients and in extensive studies." (PMID 37089558, 2023). "The serum BDNF has been investigated in several clinical manifestations of FM and also seems to be associated with some, such as depression, mood disorders, and dysfunctional eating behavior." (PMID 38127937, 2023). "The abnormal expression levels of functional proteins are closely related to depression susceptibility, including brain-derived neurotrophic factor (BDNF), postsynaptic density 95 (PSD-95), synaptophysin (SYN), and protein kinase M zeta (PKMZ)." (PMID 37179843, 2023).
depression (continued). "The mammalian target of rapamycin (mTOR), as a downstream cascade of BDNF, had been implicated in protein synthesis-dependent synaptic plasticity and can be interrupted in depression." (PMID 37308476, 2023). "The BDNF pathway plays an important role in neuroplasticity, and it has been shown that increased BDNF levels are associated with reduced symptoms of depression in pre-clinical studies." (PMID 37892388, 2023). "One of the mechanisms considered to affect BDNF bioavailability in the brain and, therefore, underlie depression is a single nucleotide polymorphism in the BDNF gene (Val66Met)." (PMID 34590201, 2023). "In this review, we will focus on the role of BDNF in major depression disorder serotonergic imbalance and associated stress conditions, particularly hypothalamic–pituitary–adrenal (HPA) axis dysregulation and oxidative stress." (PMID 37631295, 2023). "Brain-derived neurotrophic factors (BDNF) can reverse defects in synaptic plasticity caused by stress, thereby enhancing flexibility against depression." (PMID 37091719, 2023). "We aimed to evaluate the differential impact of ketamine and esketamine on serum BDNF levels and its association with response patterns in treatment-resistant depression (TRD)." (PMID 34904800, 2023). "The association between the BDNF pathway, depression, and sleep should be further studied in IBD, as it seems to modulate the disease course." (PMID 36984890, 2023). "A dysfunctional or damaged neurotransmission system in the brain, specifically involving 5-HT and BDNF, are closely associated with depression." (PMID 37692389, 2023). "Recently, research proved a correlation between BDNF levels in the nucleus accumbens and the susceptibility to induced stress (e.g., defeat stimulation), causing social avoidance and anxiety-like and depression-like behaviours." (PMID 37108250, 2023). "Both humans and mice with the BDNF val66met allele are more vulnerable to stress-induced anxiety and depression." (PMID 36982638, 2023). "The combination of 5-HT1A GG and BDNF GA + Aa genotypes is associated with a significantly increased risk of depression." (PMID 37140907, 2023). "For example, impairments in BDNF concentration and expression are associated with neuropsychiatric diseases such as depression, as well as neurodegenerative diseases such as Alzheimer’s disease, Parkinson’s disease, and Huntington’s disease." (PMID 37108547, 2023). "There was some evidence that this exposure was associated with differential BDNF methylation, even after adjustment for age, sex, education, depression, and morbidity, although the direction of association was not consistent." (PMID 36911114, 2023). "The biomarkers commonly associated with the pathomechanism of depression related to microbial etiopathogenesis include pro-inflammatory cytokines, cortisol, BDNF, and kynurenine." (PMID 36986112, 2023). "Repeated exposure to social defeat stress in mice elevates BDNF levels in the Nac, which is associated with heightened susceptibility to mood disorders like anxiety and depression." (PMID 37997979, 2023). "The consequence of this BDNF decline is neuronal loss and a slowing of the neurogenesis processes, which in turn are possible mechanisms in the pathogenesis of depression." (PMID 37895349, 2023). "According to the neuroinflammatory theory of depression, IL-6 and BDNF remain closely related, as chronic neuroinflammation is considered to cause a decrease of BDNF level in the brain." (PMID 34590201, 2023). "Both basic and clinical evidence indicate that depression is associated with several structural and neurochemical changes in which levels of neurotrophins, especially brain-derived neurotrophic factor (BDNF), are altered." (PMID 36829840, 2023). "We have previously reported interacting effects between BDNF variants and buccal promoter I methylation in late‐life depression." (PMID 36737401, 2023).
depression (continued). "The brain-derived neurotrophic factor (BDNF) gene is associated with memory disorders, depression, moral emotions, features of perception of affective visual scenes, regulation of emotions, and stress resistance." (PMID 36699706, 2023). "BDNF gene polymorphisms are also linked to HPA axis modulation in major depressive disorder, affecting antidepressant treatment response." (PMID 37631295, 2023). "In recent years, as part of the search for better diagnostic and therapeutic methods for depression, numerous scientific papers have been produced linking mood disorders and antidepressant effects to BDNF and its receptor TrkB." (PMID 36831706, 2023). "Another study indicated that 12 weeks of SI downregulated hippocampal BDNF expression was associated with anxiety- and depression-like behavior." (PMID 37895171, 2023). "A low production of brain-derived neurotrophic factor, a peptide implicated in synaptic plasticity and neuronal survival, has been observed in patients with depression." (PMID 37242244, 2023). "Animal models of stress have demonstrated that depression-like behavior is associated with reduced BDNF expression in certain murine brain areas." (PMID 37719598, 2023). "Numerous studies have identified an association between psychiatric disorders, in particular depression, and altered BDNF promoter methylation." (PMID 36911114, 2023). "For example, certain genetic variations, such as single nucleotide polymorphisms (SNPs), in the BDNF gene have been linked to an increased risk of developing conditions like Alzheimer's disease, depression, schizophrenia, and bipolar disorder." (PMID 37759083, 2023). "For instance, BDNF decrease after stroke is associated with poor long term functional outcome and development of post stroke depression; further, low level of BDNF is associated with increased risk of stroke." (PMID 37719764, 2023). "Mouse knock-out models of BDNF show severe synaptic impairments and downregulation of the gene is linked to major depressive disorder and chronic stress states." (PMID 37239811, 2023). "Depression is also associated with a decrease in BDNF, demonstrated by post-mortem analysis in the PFC of depressed individuals and in animal models of depression." (PMID 37152431, 2023). "Processes of hippocampal neurogenesis and neuroplasticity, largely controlled by neurotrophins such as BDNF, are considered today a hallmark of depressive disorder and antidepressant action." (PMID 37438361, 2023). "Based on this analysis, BDNF was mainly associated with different depressive disorders, alcoholic intoxication, and mood disorders, while the evidence provided by the PsyGeNet database was weak for alcoholic intoxication." (PMID 37252132, 2023). "Preclinically, in a post-stroke depression rat model, intranasal delivery of a BDNF-encoding adeno-associated viral vector (AAV-BDNF) increased BDNF mRNA and protein in the prefrontal cortex, alleviating depressive-like symptoms." (PMID 35887357, 2022). "BDNF is widely accepted as being critical for learning and memory, cognitive function and mood regulation, and the expression of mature BDNF peptides in the hippocampus has been proven to be associated with depression." (PMID 35334870, 2022). "This leads to an enhancement of intracellular calcium, which triggers Ca-calmodulin kinase 2 phosphorylation and ultimately elicits an increase in brain-derived neurotrophic factor (BDNF) within the nucleus accumbens, a region highly implicated in depression." (PMID 35681521, 2022). "When considering both BDNF A carrier and GG groups, the studies indicate the association of higher neuroticism and higher depression trait and related symptoms of anxiety and stress, which seems to be evidence of shared genetic risk among these dimensions." (PMID 35955088, 2022).
depression (continued). "Deyama and Duman review the literature demonstrated that depression is associated with reduced levels of BDNF, contributing to neuronal atrophy in the mPFC and hippocampus, and reduced hippocampal adult neurogenesis." (PMID 35664490, 2022). "Detection of key BDNF variants via genomic analysis of rs6265 in peripheral blood samples has shown to be more specific in identifying depression in certain populations." (PMID 36075922, 2022). "Regarding sex, one study on the association between BDNF levels and major depressive disorder reported that, in females, BDNF levels decline with age while remaining stable in males." (PMID 35836661, 2022). "For example, neurological disorders, impaired cognition, dementia, and depression are associated with lower levels of circulating brain-derived neurotrophic factor (BDNF), which can be mitigated by exercise." (PMID 36551984, 2022). "Disturbance or a reduction in BDNF causes neuronal plasticity to malfunction, as well as a reduction in excitatory neurons and glutamate, which can lead to depression." (PMID 36217471, 2022). "A total of 3123 participants from the PISMA-ep study were genotyped for the BDNF Val66Met polymorphism, of which 209 had depression." (PMID 35206257, 2022). "Among Chinese Han adolescents after the 2008 Wenchuan earthquake, there was evidence of a longitudinal association with depression between the Val66Met SNP in the brain derived neurotrophic factor (BDNF) gene and sex." (PMID 36741030, 2022). "BDNF is associated with adult neurogenesis and reduced levels of BDNF have been implicated in depression." (PMID 35848938, 2022). "The results of many clinical and animal studies confirm that BDNF and inflammation are two important risk factors in the pathogenesis of depression." (PMID 36142325, 2022). "In another study, higher BDNF methylation levels at exon I and exon IV were associated with major depression." (PMID 35836661, 2022). "A significantly low level of BDNF in blood has been linked to depression, while pharmacological treatment of the condition increases serum BDNF levels." (PMID 35626632, 2022). "On the other hand, depression is associated with reduced levels of neurotransmitters such as serotonin, dopamine, and noradrenaline, with altered tryptophan metabolism and BDNF levels." (PMID 35631252, 2022). "FXR, in turn, inhibits expression of genes encoding the neurotrophic factors TrkB and BDNF, which are highly implicated in the pathogenesis of depression." (PMID 36339629, 2022). "A common SNP of BDNF, rs62265, is a missense mutation that has been associated with anxiety, major depression, suicide, and neurodegenerative disease, as has dysregulation of mTOR signaling." (PMID 35444632, 2022). "ERK is one of the downstream BDNF pathways that is implicated in the regulation of mood and behavior in the depression model that mediates the effects of antidepressants." (PMID 36014336, 2022). "Some studies reported that lower blood BDNF levels were associated with a higher incidence of dementia and depression in CHF patients." (PMID 36490252, 2022). "In this sense, an overexpression of hippocampal FXR seems to cause depression-like symptoms and reduced BDNF levels in rats." (PMID 35050172, 2022). "Evidence indicated that BDNF and its receptor (tropomycin receptor kinase B) play a crucial role in the pathophysiology of depression and the associated therapeutic mechanisms." (PMID 36051440, 2022). "Peripheral and central BDNF levels are reduced in MS, and are associated with signs of depression and anxiety due to reduced release of synaptic proteins and neurotransmitters (monoamines and opioids)." (PMID 35492581, 2022). "The gradual evolution of the association between depression and BDNF from the field of synaptic plasticity to the field of oxidative stress and neuroinflammation was revealed." (PMID 36291673, 2022).